RRP36 (ribosomal RNA processing 36)
Description:
Involved in the early processing steps of the pre-rRNA in the maturation pathway leading to the 18S rRNA.
Synonyms: C6orf153; dJ20C7.4
Tractability: PROTAC: ubiquitination databases record sites on it.
Gene: Protein-coding gene on chromosome 6 (43,021,593 to 43,034,156, forward strand). Ensembl gene ENSG00000124541.
Subcellular location: Nucleus, nucleolus
Subcellular location (Human Protein Atlas): Nucleoli; Nucleoplasm
Pathways (Reactome):
Metabolism of RNA: Major pathway of rRNA processing in the nucleolus and cytosol; rRNA modification in the nucleus and cytosol
Gene Ontology:
Molecular function: RNA binding
Biological process: ribosomal small subunit biogenesis; rRNA processing; maturation of SSU-rRNA from tricistronic rRNA transcript (SSU-rRNA, 5.8S rRNA, LSU-rRNA)
Cellular component: nucleolus; nucleoplasm; 90S preribosome
Genetic constraint (gnomAD): Loss-of-function variants: 40 observed, 37.39 expected, observed/expected ratio (o/e) 1.07, 90% interval 0.83 to 1.39. The upper end of that interval is the gene's LOEUF score, 1.39, which puts it in group 5 of 6, group 1 being the genes least tolerant of losing a copy. Missense variants: 300 observed, 298.33 expected, observed/expected ratio (o/e) 1.01, 90% interval 0.91 to 1.11. Synonymous variants: 114 observed, 114.75 expected, observed/expected ratio (o/e) 0.99, 90% interval 0.85 to 1.16.
Homologues: Orthologues: chimpanzee RRP36 (99% identical), macaque RRP36 (97% identical), pig RRP36 (84% identical), rabbit RRP36 (78% identical), mouse Rrp36 (76% identical), rat Rrp36 (76% identical), guinea pig RRP36 (73% identical), zebrafish rrp36 (46% identical), Drosophila melanogaster CG8461 (28% identical), Caenorhabditis elegans T22H9.1 (24% identical).
Diseases named in the same sentence as RRP36 in open-access papers:
RRP36 is named in the same sentence as 10 diseases in open-access papers, as found by Europe PMC text mining. Sharing a sentence is not in itself a finding about the gene and the disease.
RRP36 shares sentences with these, for which no sentence is quoted: colon cancer (1 paper); glioma (1); infection (1); Insulin resistance (1); multiple sclerosis (1); neuroblastoma (1); neurodegenerative disease (1); Parkinson disease (1); spinocerebellar ataxia type 2 (1); type 1 diabetes (1).